INS (insulin)
Diseases named in the same sentence as INS in open-access papers (continued):
Sharing a sentence is not in itself a finding about the gene and the disease.
Obesity (continued). "This is a very important pathway in obesity since increased circulating leptin levels lead to development of leptin resistance by chronic activation of JAK/STAT3 in the CNS, whereas in the peripheral organs chronic IL-6-induced JAK/STAT3 impairs insulin action." (PMID 29170528, 2017). "Despite hyperinsulinemia, intracerebroventricular administration of insulin antagonists did not affect renal sympathetic nerve activity in experimental animals, adding to the evidence that insulin does not promote obesity hypertension by chronically stimulating the SNS." (PMID 28966594, 2017). "Intake of quercetin reduced body weight gain and attenuated serum insulin levels by reducing Firmicutes/Bacteroidetes ratio and inhibiting the growth of bacterial species Erysipelotrichaceae, Bacillus and Eubacterium cylindroides, which correlated with HFD-induced obesity." (PMID 29167659, 2017). "While beta oscillatory activity and coherence clearly differentiate between the two groups our investigation does not allow to clarify if obesity itself, high fat diet exposure or insulin resistance are the main drives behind the observed different electrophysiological patterns." (PMID 29138510, 2017). "The impact of obesity on pancreatic insulin stores has not been examined in previous studies." (PMID 28887444, 2017). "This larger drug demand could be due to the negative impact of overweight/obesity on tissue-insulin sensitivity." (PMID 29261739, 2017). "In T2DM patients with common multifactorial obesity, exogenous leptin administration does not seem to improve insulin sensitivity, possibly due to the resistance to leptin action, in a paradigm somehow concordant with what we have found in our observational study." (PMID 28626772, 2017). "On the other hand, while androgens, including testosterone, can improve insulin sensitivity in males, neither castration (Macotela, Boucher, Tran, & Kahn, 2009) nor depletion of androgens leads to obesity or T2DM‐like symptoms in animal models." (PMID 28638713, 2017). "As insulin is a key regulator of lipogenesis, it is not surprising that genes involved in insulin secretion and signaling are amongst the important candidate genes for the obesity phenotype." (PMID 28763444, 2017). "TQ administration (20 mg/kg/bw/day) to the Diet-Induced Obesity (DIO) mice reduced their diabetic phenotype by decreasing fasting blood glucose and fasting insulin levels, and improved glucose tolerance and insulin sensitivity as evaluated by oral glucose and insulin tolerance tests (OGTT and ITT)." (PMID 28950020, 2017). "Thus, we are not able to discriminate the effects of insulin stimulation, obesity, or altered substrate availability." (PMID 28252104, 2017). "We found that the Sprague-Dawley rats did not gain weight after 6 weeks high-fat diet exposure, and did not develop the metabolic hallmarks of obesity that were seen in the Long-Evans rats, such as increased percent body fat and elevated plasma leptin, insulin, and leptin/adiponectin ratio." (PMID 28871134, 2017). "Since MSG hypothalamic lesions do not enhance food consumption, but lead to obesity and insulin resistance in skeletal muscle and adipose tissue, this effect contributes to increased plasma NEFA levels, due to increased lipid release from adipose tissue, which enhances the FA source to the liver." (PMID 28380195, 2017). "Previous data suggested that lpl expression and activity in obese subjects are downregulated in an insulin-resistant compared to an insulin-sensitive state, and that an increase of lipoprotein lipase in adipocytes improves glucose metabolism in HFD-induced obesity." (PMID 28327129, 2017). "When stratified according to nutritional status, we found progressively impaired values for fasting insulin, HOMA-IR and HOMA-β with increasing severity of obesity, while CRP presented a significant difference only at obesity level I and total cholesterol at obesity level III." (PMID 29116305, 2017).
Obesity (continued). "Patients in our cohort tended to have obesity-related comorbidities, which were long-standing, with a tendency to be on a greater number of medications, were more likely to use CPAP or BiPAP to control OSA, and were more likely to be on insulin for T2DM control." (PMID 28858079, 2017). "SBP, DBP, fasting plasma glucose, fasting plasma insulin, HOMA2-IR, TG and TG/HDL-C ratio were significantly higher with weight status shift escalation, regardless of BMI system (all Ptrend < 0.05), whereas HDL-C concentrations were significantly lower from normal weight to obesity (Ptrend < 0.001)." (PMID 29166889, 2017). "In the model, interventions that could reverse the insulin resistant state were not related to obesity, beta cell functionality, insulin production or insulin action but to a set of behavioural and neuro-endocrine targets." (PMID 28767672, 2017). "Further, it stimulates the adiponectin secretion in obesity animal model and humans which activating the gene responsible for adipocyte differentiation. muscle and adipose tissue possess the two kinds of glucose transporter such as GLUT-1 and GLUT-4 in which GLUT-4 is an important insulin regulator." (PMID 27604997, 2016). "Up to now, no studies have investigated how insulin influences perioperative myocardial depression in overweight and obesity, but we hypothesized a beneficial effect." (PMID 27651131, 2016). "Insulin, which drives growth in the prenatal period, has been cited as a possible mechanism behind the “growth without GH” syndrome, as obesity-induced hyperinsulinemia may stimulate hepatic production of IGF-I." (PMID 26937243, 2016). "The presence of fasting hyperglycaemia despite normal body weight and body composition may suggest a primary pancreatic issue or skeletal insulin resistance not mediated by obesity." (PMID 27547968, 2016). "We were unable to properly test the hypothesis that prevention of HFD-induced hyperinsulinemia would protect against obesity using this male mouse model, due to non-uniform effects of reducing Ins2 gene dosage on circulating insulin in Ins1-null males." (PMID 27055260, 2016). "Moreover, MetS components which are indices of obesity and lipid metabolism (i.e. waist circumference, BMI, HDL-cholesterol and triglycerides), as well as insulin levels mediate, but do not abolish the association between adiponectin and MetS." (PMID 27567677, 2016). "Thirdly, hyperinsulinemia and decreased insulin sensitivity as part of the metabolic syndrome may also form a necessary link between obesity and hypertension, although the interrelation is still not fully known." (PMID 26927144, 2016). "However, VBM insulin sensitivity was not affected regardless of offspring maternal obesity status during pregnancy." (PMID 27669153, 2016). "Therefore, in our cohort, obesity was significantly related to elevated salivary insulin concentration but not to elevated salivary glucose concentration." (PMID 27069678, 2016). "Interestingly, this was accompanied by a partial reduction in adiposity and hepatic lipid concentrations, indicating that obesity and lipotoxicity per se do not necessarily maintain the glucose intolerant and insulin resistant state in HFD fed mice." (PMID 27273128, 2016). "Taking advantage of a high phenotypic variation in diet-induced obesity in C57BL/6J mice, 12-week-old male and female mice (n = 155) were fed a high-fat diet (lipids ~32 wt%) for a period of 10 weeks, while body weight gain (BWG) and changes in insulin sensitivity (ΔHOMA-IR) were assessed." (PMID 27183228, 2016). "Mice lacking PTP1B exhibit increased insulin sensitivity and are resistant to obesity." (PMID 27095436, 2016). "Thus, obesity itself promotes inflammation and potentiates atherogenesis independent of effects on insulin resistance or lipoproteins." (PMID 27378920, 2016).
Obesity (continued). "Obese subjects, regardless of whether they were insulin-sensitive or insulin-resistant, had moderate grade I obesity and had equivalent BMI, total fat mass, body adiposity index, visceral adiposity index." (PMID 27111539, 2016). "Our findings suggest that in obesity, insulin and IGF1 signaling pathway cross-talks with IL-17 signaling pathway through suppressing GSK3 activities, thus enhancing IL-17-mediated inflammation and contributing to the chronic inflammatory status commonly seen in obesity." (PMID 26871944, 2016). "The diet-induced obesity in our wild-type mice, with mean body weights 20% above chow-fed controls, was not accompanied by changes in fasting glucose or insulin levels, but changes were seen in circulating cytokines associated with obesity: leptin, resistin and MCP-1." (PMID 27448965, 2016). "Furthermore, in mice lacking raptor in adipose tissue, an increased insulin sensitivity and resistance to diet-induced obesity were found." (PMID 27826244, 2016). "In our previous study, the Ins1+/−:Ins2−/− genetic manipulation resulted in lifelong prevention of hyperinsulinaemia, which precluded an assessment of whether anti-obesity effects would persist without sustained repression of insulin." (PMID 26155745, 2015). "With regards to obesity, it was shown that feeding 4-week-old C57BL/6J mice a 40% high-fat diet consisting compared to the control group receiving a control diet having 14% fat had significantly increase body weight with increased area under the curve for both glucose and insulin tolerance tests." (PMID 26569331, 2015). "In summary, Adv36 may serve two different purposes, on the one hand, to explain the pathophysiology of certain cases of obesity and, on the other hand, to provide a potential weapon for improving insulin resistance, regardless of the consumption of fat." (PMID 26184280, 2015). "We then corroborated that most of the subjects showing low systemic levels of IL-10 and high AHI value also had increased insulin resistance, suggesting a direct association among OSA, anti-inflammatory factors, and metabolic abnormalities irrespective of obesity." (PMID 25944984, 2015). "With regard to the monogenic model of obesity, the ob/ob mice exhibit a high body weight and food intake, and similar to the DIO rats, the ob/ob mice display a significant increase in insulin, glucose, and cholesterol levels with respect to WT controls and high levels of inflammatory markers in WAT." (PMID 26568663, 2015). "In our multivariable analysis, we adjusted for obesity (BMI), diet and physical activity, but the main differences between the South Asian and white participants remained, in terms of both the slope difference in FG and the large intercepts regarding PLG, insulin and insulin sensitivity." (PMID 25431266, 2015). "Interestingly, a similar improvement in glucose tolerance and insulin sensitivity was detected in LMP7−/− mice fed with normal chow diet, indicating that LMP7 is involved in insulin sensitivity independent of obesity." (PMID 26515636, 2015). "Therefore, it is highly desirable to find new anti-diabetic agents that stimulate glucose uptake by adipose or muscle cells but, unlike thiazolidinedione or insulin, do not induce obesity or other side effects." (PMID 25652009, 2015). "Thus, the findings from our investigation suggest that Deepure tea may be a desirable food for preventing insulin resistance and ectopic lipid accumulation, especially in HFD-induced obesity." (PMID 26504484, 2015). "Besides nutritionally-induced obesity, we included genetically obese ob/ob mice and their wild-type littermate controls in our experiments, mainly as a control for determining the effects of HFD on metabolic parameters like insulin resistance." (PMID 26176620, 2015).
Obesity (continued). "Mechanistic studies in experimental models of disease have shown that MIF contributes to insulin function in non-pathological glucose homeostasis (i.e., in absence of obesity or disease) but its role is less clear when metabolic stress and pathological processes come into play." (PMID 26124760, 2015). "Apart from the anabolic properties of insulin, contributing to increased size, hyperinsulinemia and/or leptin resistance in OGDM may also alter hypothalamic appetite regulation, resulting in increased food intake and obesity." (PMID 25478935, 2015). "In addition, other surrogate markers of the obesity including insulin, glucose, insulin/glucose ratios, HDL cholesterol and triglycerides were not significantly different in women with PCOS compared with controls in our study." (PMID 25972770, 2015). "Therefore, (emerging) obesity can advance puberty in females without insulin sensing by kisspeptin neurons." (PMID 25946091, 2015). "The inflammatory response of the hypothalamus to HFD-induced obesity can lead to decreased leptin and/or insulin sensitivity, which not only results in negative consequences in the regulation of food intake and energy balance, but also leads to secondary complications, such as type 2 diabetes." (PMID 25859240, 2015). "In muscle biopsies from patients with T2D (daily treatment with insulin prior to surgery), the decrease in the mRNA expression level of BRS-3 compared to the levels of the normal subjects was similar to the decrease detected in the muscle tissue sections from patients with obesity." (PMID 25653074, 2015). "Although the pathophysiology underlying the development of dyslipidemia in obese children is multifactorial and not yet completely defined, insulin resistance has been hypothesized to play a major role in the relationship between dyslipidemia and obesity." (PMID 25663838, 2015). "Thus, the decreased production of ZAG in human obesity would be merely a reflection of increased fat mass and not directly related to insulin resistance." (PMID 26068931, 2015). "Data obtained from experiments conducted in diet-induced obesity models have shown that yerba maté suppresses body weight gain and visceral fat accumulation and decreases serum levels of cholesterol, triglycerides, LDL cholesterol, glucose, insulin, pancreatic lipase and leptin." (PMID 25621503, 2015). "However, it is worth noting that several studies including ours suggest that insulin per se is not essential or sufficient to explain behavioral alterations occurring in obesity." (PMID 26190966, 2015). "It is also hypothesized that obesity and inactivity rather than age per se is the primary determinant of age-related declines in insulin sensitivity." (PMID 25790476, 2015). "Strikingly, the fasting insulin levels of calorie restricted Bbs2-/-, Bbs4-/-, and Bbs6-/- mice are significantly elevated indicating that the hyperinsulinemia associated with BBS is independent of obesity." (PMID 26103456, 2015). "Adjustment for obesity indices (BMI, total, android, gynoid, or android/gynoid fat ratio, waist or waist/hip ratio) or for sex did not eliminate group differences in indices of insulin sensitivity, C-peptide secretion and plasma IL-1Ra." (PMID 26417659, 2015). "The NEFA composition also varied with overweight/obesity but not with insulin sensitivity." (PMID 26011768, 2015). "Unlike glucocorticoids, ApN increases insulin sensitivity, does not induce muscle atrophy but rather reduces proteolysis, upregulates utrophin (our own data) and enhances the myogenic program, prevents obesity, and protects against hypertension." (PMID 26257862, 2015). "Xu and colleagues performed in vivo studies in obese mice and hypothesized that after a certain threshold of obesity, macrophage recruitment (through MCP-1 secretion) is improved, resulting in a feedback loop where insulin signaling is impaired, leading to adipocyte lipolysis and necrosis." (PMID 25526965, 2014).
Obesity (continued). "Altough inflammation might not impact on insulin sensitivity in the onset phase of obesity, inflammation within adipose tissue has been shown to have deleterious effects on systemic insulin sensitivity in models of chronic obesity." (PMID 25233471, 2014). "The obesity model used in this study was generated by monosodium glutamate (MSG) neonatal neuro-intoxication, which has been reported to induce a hypothalamic lesion in the arcuate nucleus and neuro-endocrine alterations in insulin and leptin signaling, among other effects." (PMID 24979131, 2014). "However, VPA-treated patients had higher serum insulin concentrations, independent of BMI, suggesting that hyperinsulinemia is not a consequence of obesity." (PMID 25078464, 2014). "For example, a signalling pathway involving BMP4 and its receptor BMPR1A influences insulin secretion and may contribute to obesity; mice lacking the HMGA2 homolog had a reduction in fat mass and were resistant to diet induced obesity." (PMID 24823714, 2014). "In obesity, elevations in saturated fatty acids increase DNMT3b expression, leading to DNA methylation at the PPAR-γ1 promoter; this may contribute to deregulated adipose tissue macrophage polarisation, inflammation, and insulin resistance." (PMID 24967364, 2014). "The potential clinical value of the reversible role in the insulin/leptin receptor phosphorylation and signaling provides a major stimulus to the realization that inhibiting PTP1B can alleviate insulin resistance, normalize glycaemic control and address both Type 2 diabetes and obesity." (PMID 24831294, 2014). "At high concentrations, as found in obesity, IL-1Ra could have deleterious effects independent of IL-1R1 since IL-1R1 KO mice display improved insulin sensitivity after IL-1Ra knock-down." (PMID 25244011, 2014). "Therefore, it is tempting to speculate that these signals are also responsible for the induction of NKG2D ligands in the adipose tissue in vivo given that insulin and TNF-α levels are known to be elevated in obesity." (PMID 25333972, 2014). "The robust propensity to obesity in Ossabaw miniature swine clearly makes this breed superior to other laboratory animal swine, such as the Yucatan miniature pig, which show minimal obesity and complete absence of insulin resistance after long-term, high-calorie diets." (PMID 25215301, 2014). "However, elevated saturated FA is sufficient to induce lipotoxic stress in the hypothalamus and attenuate responses to insulin and leptin negative feedback, contributing to dietary-induced obesity (DIO) and attendant metabolic dysfunction." (PMID 25541737, 2014). "In addition, as ASP is an important regulator of postprandial lipemia an increase in basal plasma lipids in obesity could be the consequence of putative ASP resistance, analogous to the hyperglycemia in insulin-resistant states." (PMID 24523571, 2014). "Although we cannot rule out an effect on insulin sensitivity upon specific inhibition of the MAP3K8 signalling pathway during obesity, future studies should rather illuminate the role of other inflammatory pathways and kinases in adipose tissue affecting systemic metabolic health." (PMID 24586913, 2014). "Moreover, only in the absence of obesity, insulin significantly elevates cGMP concentration in platelets contributing to platelet inactivation following the adhesion." (PMID 25601838, 2014). "Thus while exercise does increase the effect of insulin on glucose metabolism in both lean and obese individuals, it does not normalize the cellular deficit due to obesity." (PMID 24772374, 2013). "Several studies sustain the hypothesis that sleep apnea per se deteriorates insulin sensitivity, independent of obesity." (PMID 23951064, 2013).